CETP (cholesteryl ester transfer protein)
Diseases named in the same sentence as CETP in open-access papers (continued):
Sharing a sentence is not in itself a finding about the gene and the disease.
Hypercholesterolemia (40 papers, 2011 to 2026). An increased concentration of cholesterol in the blood. "It was found that gender and CETP gene polymorphism were both associated with the pathological distribution of TG levels after oral fat tolerance test in heterozygotes for familial hypercholesterolemia (n = 80)." (PMID 35498036, 2022). "CKD519, a selective inhibitor of cholesteryl ester transfer protein(CETP), is undergoing development as an oral agent for the treatment of primary hypercholesterolemia and mixed hyperlipidemia." (PMID 31311144, 2019). "CKD519, a selective inhibitor of CETP, is undergoing development as an oral agent for the treatment of primary hypercholesterolemia and mixed hyperlipidemia." (PMID 31311144, 2019). "The hCETP transgenic pigs showed hypercholesterolemia, and metabolomic analysis found CETP-related metabolic components." (PMID 28893253, 2017). "We detected CETP protein in the plasma of all human liver chimeric mice, with highest levels in familial hypercholesterolaemia chimeric mice fed Western diet." (PMID 26081744, 2015). "We designed a four-week parallel controlled intervention on apolipoprotein E3 Leiden cholesteryl ester transfer protein (ApoE*3Leiden.CETP) transgenic mice with mild overweight and hypercholesterolemia." (PMID 21611179, 2011). "Only medications that inhibit cholesteryl ester transfer protein (CETP), angiopoietin-related protein 3 (ANGPTL3), and apolipoprotein C-III (apoC-III) have lately been explored in clinical trials, despite the fact that about 80 genes are linked to hypercholesterolemia." (PMID 36138787, 2022). "Moreover, adult patients with hypercholesterolemia presented an increased transport rate of CETP." (PMID 34222380, 2021). "In the future, we plan to study plaque regression in the E3L.CETP-mice model, as due to the introduction of the CETP their lipoprotein metabolism is closer to the general human situation and thus makes the results readily translatable into humans beyond familial hypercholesterolemia." (PMID 30813320, 2019). "APOE∗3-Leiden.CETP mice exhibited elevated plasma VWF levels compared with WT mice, alongside hypercholesterolemia and aortic atherosclerosis." (PMID 40093962, 2025). "Interestingly, the just-mentioned vaccine approaches significantly ameliorated hypercholesterolemia in mouse models, such as APOE∗3Leiden.CETP mice used by the AFFiRiS group for developing the AFFITOPE® vaccine." (PMID 34504898, 2021). "Although HDL levels are regulated by cholesteryl ester transfer protein, hepatic TG lipase and lipoprotein lipase etc., the increased HDL and LDL levels may be an event secondary to hypercholesterolemia induced by feeding HFCBD in mice." (PMID 22989092, 2012). "ApoE*3Leiden.CETP mice with mild hypercholesterolemia were divided into SUB885C-, rimonabant- and non-treated control groups." (PMID 22291936, 2012). "The traditional Japanese diet consists of a high intake of fish, miso, soy sauce, and vegetables; contributes to the prevention of ASCVD; lowers the risk for hypercholesterolemia, CAD, and non-HDL-C and increases serum HDL-C levels by genetic deficiency of cholesterol ester transfer protein (CETP)." (PMID 38956709, 2024). "Following identical experimental conditions, FACS analysis revealed that juvenile rats had higher levels of cd45- [cd34+/kdr+]EPCs/ml than 4 m-old rats regardless of transgenic expression of human cholesteryl ester transfer protein, which induces significant hypercholesterolemia on regular rat chow." (PMID 23383116, 2013).
Insulin resistance (40 papers, 2006 to 2025). Increased resistance towards insulin, that is, diminished effectiveness of insulin in reducing blood glucose levels. "We observed that transgenic expression of CETP in female mice was associated with increased muscle glycolysis during fasting and protection against diet-induced insulin resistance." (PMID 26313355, 2015). "Our results show that the B1B1 genotype of the Taq1B CETP polymorphism is associated with more insulin resistance, higher post-OGTT glucose levels and an increased risk of T2D." (PMID 22073289, 2011). "Previously, we proposed that the contribution of the Taq1B CETP polymorphism on insulin resistance could be mediated by an increased flux of FFAs from HDL particles to the liver." (PMID 22073289, 2011). "Overall, the deficiency of cholesteryl ester transfer protein leads to abnormal triglycerides and cholesterol storage and downregulates the membrane ratio of free cholesterol/protein associated with the induction of insulin resistance and the changes in adipocytokines synthesis." (PMID 34299261, 2021). "Several of the lipid‐associated genic hits like CETP, GCKR, and GLP1R are known to function in lipid metabolism, glucose metabolism, type 2 diabetes, and insulin resistance." (PMID 40665476, 2025). "It was previously shown that insulin resistance leads to low HDL-C levels by enhancing CETP-mediated exchange of TG and cholesterol ester between HDL and triglyceride-rich lipoproteins." (PMID 41401179, 2025). "To date, scientific literature has not described a specific mechanism of action that clarifies the effect of TFA intake on insulin resistance in carriers of the GG genotype of the SNP 708272 of the CETP gene." (PMID 39519516, 2024). "This study also suggested that, while increasing HDL-cholesterol level, inhibition of serum CETP activity leads to metabolic dysregulation such as fatty liver, insulin resistance, and inflammation." (PMID 35082691, 2021). "In this study, we show that female transgenic mice expressing the human CETP minigene containing its natural regulatory elements are protected from diet-induced insulin resistance." (PMID 35082691, 2021). "People with obesity-associated insulin resistance have changes in some key enzymes involved in HDL metabolism, like cholesteryl ester transfer protein, lecithin/cholesterol acyltransferase, hepatic lipase, and phospholipid transfer protein." (PMID 34299261, 2021). "Mounting evidence has shown that CETP has important physiological roles in adapting to chronic nutrient excess, specifically, to protect against diet-induced insulin resistance." (PMID 35082691, 2021). "We previously showed that the overexpression of simian CETP in mice protects against diet-induced insulin resistance." (PMID 35082691, 2021). "The transgenic expression of human CETP in mice limits liver lipid accumulation and improves insulin resistance during high-fat diet feeding in females." (PMID 35082691, 2021). "Supporting these notions, a recent study demonstrated that CETP inhibitor gives rise to fatty liver and insulin resistance in CETP-expressing transgenic mice fed with a high-fat diet." (PMID 31979310, 2020). "Individuals with higher CETP mass present higher values of fasting insulin and HOMA insulin resistance index compared with individuals with lower CETP mass." (PMID 26758205, 2016). "Indirectly, elevated FFAs could lead to insulin resistance and modify cholesteryl ester transfer protein (CETP) activity, which have significant roles in HDL metabolism." (PMID 40535330, 2025). "Insulin resistance leads to an inhibition of lipoprotein lipase (LPL) which, along with increased cholesteryl ester transfer protein (CETP) activity, causes an increase in circulating small low-density lipoprotein (LDL) and large very-low-density lipoprotein (VLDL) particles." (PMID 41156274, 2025).
Insulin resistance (continued). "In addition, based on the previous report that overexpression of simian CETP protected against insulin resistance only in female mice, we further investigate the metabolic impact of human CETP minigene in female mice in the current study." (PMID 35082691, 2021). "Our findings for the protective roles of CETP for diet-induced fatty liver and insulin resistance specific in females may provide insight to explain why most clinical trials with CETP inhibitors failed in improving the risks for cardiovascular disease." (PMID 35082691, 2021). "In addition, multiple regression analyses identified homeostasis model assessment-insulin resistance (HOMA-IR) as an independent predictor of CETP activity, as well as ferritin concentration of Lp-PLA2 activity." (PMID 23857219, 2013). "Although the mechanism of the association between CETP and insulin resistance has not yet been precisely elucidated, previous studies showed that when a CETP inhibitor was used, HDL-C increased, and the HOMA-IR and glycemic control in type 2 diabetic patients were improved." (PMID 34503545, 2021). "Variations in the CETP gene might influence the different components of insulin resistance." (PMID 16623947, 2006). "Insulin resistance impairs HDL synthesis and function, while increased CETP activity promotes the transfer of cholesteryl esters from HDL to other lipoproteins, reducing HDL-C levels." (PMID 40535330, 2025). "Insulin resistance in T2DM promotes overproduction of triglyceride - rich VLDL particles and increases CETP activity, leading to higher triglyceride content in LDL particles and making them more susceptible to hepatic lipase degradation." (PMID 40824591, 2025). "Adipose tissue dysfunction and insulin resistance escalate lipolysis and FFA release, leading to decreased lipoprotein lipase activity and increased cholesteryl ester transfer protein expression." (PMID 39175570, 2024). "Under high triglyceride conditions such as insulin resistance, triglyceride-enriched VLDL stimulates CETP and lipases and the consequent transfer of triglycerides from VLDL to LDL, thereby raising LDL-TG." (PMID 36501072, 2022). "The E3L.CETP mice did not display insulin resistance, as evidenced by the lack of changes in the level of blood glucose concentration in the GTT." (PMID 40240752, 2025). "Mice naturally lack CETP, but we previously reported that transgenic expression of CETP increases muscle glycolysis in fasting and protects against insulin resistance with high-fat diet (HFD) feeding in female but not male mice." (PMID 26313355, 2015). "In the state of insulin resistance, ApoB degradation is inhibited, leading to an overproduction of very low-density lipoproteins (VLDL), which results in the predominance of sdLDL due to increased activity of cholesteryl ester transfer protein and hepatic lipases." (PMID 40309448, 2025). "Insulin resistance drives hepatic overproduction of VLDL particles, increasing both Apo B particle numbers and non-HDL-C, while simultaneously promoting the formation of small, dense LDL through cholesteryl ester transfer protein (CETP)-mediated lipid exchange." (PMID 40710781, 2025). "The inverse relationship between plasma triglyceride and HDL levels among insulin resistance patients could be explained by the exchange of triglycerides in the very low-density lipoproteins for HDL cholesteryl esters, a process mediated by cholesteryl ester transfer protein." (PMID 38846018, 2024). "Insulin resistance also exerts the synthesis of small dense LDL (sdLDL) and decreases HDL levels, which are created by the transferring of VLDL’s triglycerides to LDL and HDL under the catalysis of cholesteryl ester transfer protein (CETP), provoking triglyceride-rich LDL and decreasing HDL-C." (PMID 37664840, 2023).
Insulin resistance (continued). "Glycemic control alone does not prevent ASCVD, since insulin resistance leads to more production of triglyceride-rich very-low-density lipoprotein (VLDL) particles, greater cholesteryl ester transfer protein (CETP) activity, and higher hepatic lipase activity." (PMID 41373581, 2025). "CETP rs708272 GG carriers are more adversely affected by even a minimum TFA intake, experiencing significant persistence in no reducing glucose levels and insulin resistance parameters after dietary intervention." (PMID 39519516, 2024).
hyperlipidemia (39 papers, 2011 to 2025). "The objective of this study was to determine the relationships between deficient, non altered and increased CETP activity of asymptomatic adult women and postprandial lipemia." (PMID 21609439, 2011). "CETP inhibitors, particularly anacetrapib and obicetrapib combined with statins, significantly improve lipid profiles, offering potential therapeutic benefits for hyperlipidemia management and cardiovascular risk reduction." (PMID 40947782, 2025). "In conclusion, the E3L.CETP mice displayed an accelerated age-dependent impairment of the endothelial function in response to mild hyperlipidaemia as compared with the age-dependent endothelial dysfunction in the C57BL/6J mice." (PMID 40240752, 2025). "In order to find hyperlipidaemia markers in aortic proteome, a similar approach as for the identification of ageing markers was adopted, however based on comparison of E3L.CETP to C57BL/6J mice." (PMID 40240752, 2025). "This separation was more pronounced than the hyperlipidaemia-dependent differences in proteome of E3L.CETP mice vs C57BL/6J mice, either in 8-week-old or in 40-week-old mice (Fig. 4A2)." (PMID 40240752, 2025). "Note that our method’s goal is not to prepare isolated CM but to deliver CM composition and concentration data to test our CETP model in postprandial lipemia." (PMID 40562102, 2025). "This diverse cohort enables robust evaluation of CETP inhibitors’ efficacy across lipid parameters in hyperlipidemia management." (PMID 40947782, 2025). "Here, we characterise effects of mild, life-long hyperlipidaemia on age-dependent endothelial dysfunction (ED) in humanised dyslipidaemia model of E3L.CETP mice." (PMID 40240752, 2025). "In particular, young male E3L.CETP mice exhibited more pronounced changes in plasma proteomic profile which reflected lesser resilience to detrimental effects of hyperlipidaemia on endothelial function as compared to female E3L.CETP mice." (PMID 40240752, 2025). "In this study, we utilized the APOE*3-Leiden.CETP mouse, a well-established model for hyperlipidemia, characterized by increased plasma cholesterol and TG levels, that resembles lipoprotein metabolism of patients with familial dysbeta­lipoproteinemia (FD)." (PMID 31843957, 2020). "As we observe that both CL316243 treatment and cold exposure reduce hyperlipidaemia in E3L.CETP mice our results provide proof for the concept that in principle BAT activation has beneficial effects on plasma lipids." (PMID 25754609, 2015). "The regulation of metabolic pathways (contrary to DEPs involved in ageing in E3L.CETP mice—upregulation of DEPs) as well as inflammation were also the dominant processes, in which hyperlipidaemia-dependent (E3L.CETP vs C57BL/6J mice) DEPs were involved, in plasma of 8-week-old male mice." (PMID 40240752, 2025). "However, we found clear-cut hyperlipidaemia-induced changes in plasma proteome with a sex-specific profile of DEPs in E3L.CETP mice vs control mice." (PMID 40240752, 2025). "Multidirectional proteomic analyses were performed to analyse ageing-related changes in plasma (8-week-old mice compared to 28-week-old mice within the same strain of mice) and hyperlipidaemia effects in 8- and 28-week-old mice (comparison of E3L.CETP mice to age-matched control C57BL/6J mice)." (PMID 40240752, 2025). "Interestingly, in patients with elevated TG (e.g. DM patients and CAD patients with HTG or CAD patients with combined hyperlipidemia) CETP activity is positively correlated with ApoC-I concentrations, whereas in healthy controls this association was absent." (PMID 38429638, 2024).
hyperlipidemia (continued). "E3L.CETP mice are a well-established model for hyperlipidemia and atherosclerosis." (PMID 33658534, 2021). "Cd-mediated hyperlipidemia may be correlated to that of Cd-mediated up-regulation of cholesteryl ester transfer protein." (PMID 31752142, 2019). "Importantly, in the present work, we analysed the age-dependent development of endothelial dysfunction in E3L.CETP mice fed a chow diet resulting in mild hyperlipidaemia, in contrast to high fat and cholesterol-containing diets as used in a number of previous studies in this model." (PMID 40240752, 2025). "Accordingly, we suggest that the early pattern of vascular response to hyperlipidaemia at the young age may determine the accelerated ageing in E3L.CETP male mice, detected in the plasma proteome and by MRI in vivo as an accelerated progression of age-dependent endothelial dysfunction." (PMID 40240752, 2025). "Although further investigations are needed, in line with one of the hypothetical effects of the anthocyanins in the presence of hyperlipidemia, it can be speculated that the administered sour cherry extract exerted inhibition on the cholesteryl ester transfer protein (CETP)." (PMID 37686067, 2023). "Here, we investigate whether combining the hyperlipidemia drug class of cholesteryl ester transfer protein (CETP) inhibitors with the existing hyperglycemia treatment in sodium glucose transporter 2 (SGLT2) inhibitors is an effective strategy to improve glycemic control." (PMID 37398493, 2023). "Additionally, in a preclinical tg model with profound hyperlipidemia, administration of the CETP ASO demonstrated that significant reductions in plasma TG, positive effects on macrophage RCT, and reductions in CETP mRNA were associated with less accumulation of aortic cholesterol." (PMID 23801661, 2013). "However, low CETP activity leading to ApoB-containing lipoproteins TG enrichment increases lipoprotein competition to lipolysis sites with consequent lipemia augmentation, even though a reduction in receptor mediated remnant uptake could also be present." (PMID 21609439, 2011). "In contrast, in older E3L.CETP and C57BL/6J mice, either plasma or aortic proteome displayed similar pattern of vascular ageing, dominating over hyperlipidaemia-induced changes." (PMID 40240752, 2025). "Furthermore, the role of CETP in atherogenicity may be dependent on LDL receptor integrity, possibly explaining the increased LDL-c baseline levels observed in the minor allele A female carriers with hyperlipidaemia in this study." (PMID 37102051, 2023). "In CETPd the regression multivariate analysis (model A) showed that CETP was largely and negatively predicted by VLDL-C lipemia (R2 = 92%) and much less by TG, LDL-C, ApoAI, phospholipids and non-HDL-C." (PMID 21609439, 2011). "Here, we describe for the first time the CETP-mediated TG flux in the postprandial state.a.In normolipidemics, we measured a decrease of LDL and HDL-cholesterol (FC + CE) and an increase in HDL-TG in postprandial lipemia." (PMID 40562102, 2025). "In patients with CHD and hyperlipidemia the inhibition of plasma CETP by ApoC-I is blunted, which is probably due to increasing amounts of VLDL-bound ApoC-I which is less active as inhibitor of CETP than HDL-bound ApoC-I." (PMID 38429638, 2024). "The absence of cholesteryl ester transfer protein explains the difficulties with the induction of hyperlipidemia in rats." (PMID 37895942, 2023). "A loss of the negative correlation between apoC1 and CETP activity was observed in patients with type 1 or type 2 diabetes, similarly to what was reported CAD patients with hyperlipidemia." (PMID 36471375, 2022).